CXCL8 (C-X-C motif chemokine ligand 8)
Diseases named in the same sentence as CXCL8 in open-access papers (continued):
Sharing a sentence is not in itself a finding about the gene and the disease.
cancer (continued). "The development of a mutant derived from CXCL8, characterized by an augmented affinity for GAGs, represents a promising avenue in the therapeutic intervention for chronic inflammatory diseases and cancer." (PMID 40124384, 2025). "CXCR1 as a receptor for CXCL6 and CXCL8, is also a promising target for cancer treatment." (PMID 39780187, 2025). "CCL2 and CXCL8, secreted by CAFs, induce cancer cell proliferation and invasion." (PMID 40136652, 2025). "The search strategy was designed by three authors (M.M, I.Z., and S.M.)and approved by all the other scientists, combining the following medical subject headings (MeSH) terms: “interleukin-8” or “IL-8” or “CXCL-8” or “CXCL8”, and “carcinoma” or “RCC” or “cancer” or “ccRCC” or “chRCC” or “pRCC”." (PMID 40839124, 2025). "Moreover, cancer cells exposed to HT-CM display increased mRNA expression for several pro-cancerogenic agents, including CXCL8, tPA, and VEGF." (PMID 39595551, 2024). "There is growing evidence supporting a role for CXCL8 in the development of cancer." (PMID 38807156, 2024). "In addition to CXCL12, there are other chemokines that hold promise for regulating the migration of cancer cells, such as CXCL8, CXCL16, CCL2, and CXCL10." (PMID 39715221, 2024). "In an experimental model, NF-κB and mTOR coordinated radiation-induced CXCL8 secretion in cancer cells with senescence characteristics, leading to targeted migration of CD56-dim NK cells, thus linking senescence-associated CXCL8 release to innate immune surveillance of human tumors." (PMID 38421832, 2024). "Notably, CXCL8 activation of the PI3K/Akt signaling pathway is a critical process in various cancers, such as androgen-independent prostate cancer." (PMID 38791448, 2024). "This is supported by several studies, suggesting CXCL8 as the most accurate diagnostic marker to differentiate between infectious and non-infectious neutropenic fever episodes during childhood cancer treatment." (PMID 37919603, 2024). "Besides its role in cancer, CXCL8, along with CXCL1, 2, and 5 are noted for their autocrine and/or paracrine effects in reinforcing senescence." (PMID 38385965, 2024). "Furthermore, we found that 1,2-NQ upregulated CXCL8 expression through DNA demethylation of the distal enhancer and promoted cancer cell growth." (PMID 39519144, 2024). "Furthermore, (hetero)dimerization and tight regulation of transcription and translation, as well as post-translational modifications further fine-tune the spatial and temporal activity of CXCL8 in the context of inflammatory diseases and cancer." (PMID 36725964, 2023). "Besides chemokines of NF-κB signaling, the inflammatory cytokines TNF-α and LIF were highlighted to play a role in interaction with CXCL-8 in cancer development and the chemokines CXCL3 and CXCR2 in their role in cell migration." (PMID 37048115, 2023). "Cristinziano found that in ATC, cancer cells could produce the soluble mediators CXCL8/IL-8 and ROS to induce TANs to release neutrophil extracellular DNA traps (NETs), a network of cytosols and granulin, and promote the growth of cancer cells." (PMID 37345200, 2023). "In accordance with this observation, peripheral blood neutrophils from cancer patients exhibited an enhanced spontaneous migration and a greater response to CXCL8 or N-formyl-l-methionyl-l-leucyl-phenylalanine (fMLP) compared to the neutrophils obtained from healthy donors." (PMID 37444436, 2023). "While elucidation of the precise function(s) and putative binding partners of HERVH-driven calbindin in other settings will require further investigation, a clear outcome of the HERVH-driven isoform is the control of cancer cell–autonomous CXCL8 secretion both in vitro and in vivo." (PMID 37192000, 2023). "Thus, cancer cells were the main producers of CXCL1, CXCL2, and CXCL8, but cancer cell–intrinsic production of these chemokines was prevented by CALB1 expression." (PMID 37192000, 2023).
cancer (continued). "Notably, many studies together with ours have consistently shown that CXCL8 is an angiogenic polypeptide that is expressed in multiple cancers, and it is a common secretory protein that potentially mediates immune reactions in the immune system." (PMID 37898619, 2023). "Genes related to the cancer-associated adipocytes (CAA) phenotype were found induced, and these included the C–C motif chemokine ligand 2 (CCL2), interleukin-1 beta (IL-1B), and C-X-C motif chemokine ligand 8 (CXCL8)." (PMID 37833751, 2023). "Recently, IL1B has been shown to induce CXCL8 secretion in human cancer cells." (PMID 37370765, 2023). "Studies show that CXCL8 is excessively secreted in a variety of cancers." (PMID 37377954, 2023). "Given the growth defects of CALB1-deficient LUSC cell lines, autocrine CXCL8 signaling driving cancer cell–intrinsic growth is unlikely to compensate for this proliferative disadvantage or to explain the worse prognosis of CALB1-negative tumors." (PMID 37192000, 2023). "Eight cytokines (IL-1β, IL-6, IL-10, TGF-β, CCL2, CXCL8, CSF-1, and VEGF) were identified to have higher expression values in the high-risk group than in the low-risk group, which was relevant to the progression, invasion, and metastasis of cancers." (PMID 36120553, 2022). "We also showed that PTEN ablation could attenuate the decrease in phosphorylated AKT, VCAM1 and CXCL8 and cancer cell proliferation mediated by overexpression of OTUD1 in 786-O cells." (PMID 35280681, 2022). "The data suggest development of an in vivo SASP, the index of which can be measured by quantifying concurrently expressed soluble factors, including but may be not limited to EREG and CXCL8, in the peripheral flood of post-treatment cancer patients." (PMID 36202915, 2022). "In addition, CXCL1 expression was extremely correlated with CCL20, CXCL8 and CXCL3 cancer-associated chemokines expression." (PMID 35764974, 2022). "CXCL8 also induces ET formation in neutrophils, thereby enhancing cancer malignancy." (PMID 35574410, 2022). "The CXCL8 axis is beneficial for the regulation of cancer cell progression." (PMID 36497496, 2022). "The correlation between CXCL8 expression and cancer survival in TCGA cohorts." (PMID 35372515, 2022). "High expression of CXCL8 in cancer cells suggests poor survival prognosis in colorectal cancer." (PMID 36358719, 2022). "Candidate NETs-promoting mediators include G-CSF, CXCL8/IL8 in different cancer models." (PMID 35281873, 2022). "CXCL8 can mediate cancer cell proliferation both in autocrine and paracrine manner." (PMID 35372515, 2022). "Additionally, the results of the third transcript whose overexpression we determined, CXCL8, are different than expected, as an increase in its expression has been noted in many types of cancer." (PMID 35625926, 2022). "The expression of CXCL8 in endothelial cells is an important issue in cancer." (PMID 33467722, 2021). "Many studies have reported that CXCL8 is upregulated in different cancers." (PMID 33955820, 2021). "In addition to TGFB1 and IL10, gene expression of IFNG, IL6, and CXCL8 were all significantly increased (p < 0.05) in mesenchymal samples for more than half of the cancer types." (PMID 35096592, 2021). "Altogether this makes the CXCR1/2 -CXCL8 pathway a target for cancer therapy." (PMID 34944943, 2021). "More importantly, the feedback loop of secreted CXCL8 facilitates the re-population of drug resistant cancer cells that exacerbates the clinical outcome in multiple cancer types, and such resistance could be reversed with CXCL8 inhibition." (PMID 34217295, 2021). "CXCL8 is considered a potential attractive target for cancer treatment." (PMID 34025668, 2021). "Therefore, this provided an insight on the mechanism associated with HCV-HCC, namely, that it is mediated by CXCL8 to regulate the oncogene SRC, promoting a cancer-favoring environment in the progression of HCC." (PMID 34680563, 2021).
cancer (continued). "It has also been proposed that CXCL8 may be considered as a therapeutic target for cancer treatment." (PMID 34025668, 2021). "Besides, CXCL8 is a potent chemotactic factor for neutrophils, MDSCs and monocytes, which are considered immunosuppressive components in cancer-bearing hosts." (PMID 34025668, 2021). "Although the specific mechanisms underlying CXCL8-mediated cancer progression may be diverse, CXCL8 has been identified to participate in various cancers." (PMID 33954053, 2021). "CXCL8 is a potent chemotactic factor for neutrophils, myeloid-derived suppressor cells (MDSCs) and monocytes, which are considered immunosuppressive components in cancer-bearing hosts." (PMID 34025668, 2021). "Similarly, CXCL8/9/10/11 were overexpressed in CC tissues instead of para-carcinoma tissue in Biewenga Cervix Statistics." (PMID 34321012, 2021). "CXCL8 activates this classic signalling cascade in both neutrophils and cancer cells." (PMID 32730361, 2020). "Thus, when cancer cells acquire the ability to express CXCL8, it is assumed that they will enhance osteoclastogenesis during the metastatic process." (PMID 32582148, 2020). "CXCL8 promotes cancer metastasis mainly by recruiting neutrophils." (PMID 32626535, 2020). "This suggests that CXCL8 can promote the migration of cancer cells." (PMID 32201645, 2020). "Accordingly, CXCL8 is also responsible for cancer cells malignant behavior in an autocrine fashion." (PMID 32766720, 2020). "CXCL8 plays crucial roles in the development and metastasis of different cancers." (PMID 32419252, 2020). "Considering the pleiotropic effects of CXCL8 in cancer (e.g., angiogenesis), and the hypothesized mechanism of action of CXCR1 inhibition on CSC, a number of markers were investigated on core biopsy samples by IHC." (PMID 31924241, 2020). "Herein, we firstly identified CXCL8 as a hub gene related to prognosis in cancers." (PMID 33178604, 2020). "In this view, the present study was specifically aimed at evaluating whether PLX4720 (already proven to have several anti cancer effects) was also able to inhibit CXCL8 secretion which could be regarded “per se” as beneficial against cancer." (PMID 30867499, 2019). "A number of studies have investigated the effects of CXCL8 on cancer invasion and migration." (PMID 31788042, 2019). "Furthermore, CXCL8 enhances the resistance of cancer cells to anoikis, thus promoting their metastatic potential." (PMID 31805999, 2019). "In addition, cancer cell-derived CXCL1 induces the expression of CXCL8 and GRO-α in MSCs, which promotes the formation and maintenance of CSCs." (PMID 31788042, 2019). "The overexpression of CXCL8 in cancer cells has been recognized for many years." (PMID 31805999, 2019). "As CXCL8 is a potent pro-angiogenic factor that may also promote cancer growth and metastasis, it appeared that the PTPRD-CXCL8 axis may be responsible for cancer metastasis." (PMID 31805999, 2019). "Thus, phenformin exerts anti-cancer effects on both cancer cells (cell death induction) and surrounding normal cells (inhibition of CXCL8 secretion)." (PMID 31741708, 2019). "Overexpression of CXCL1 and CXCL8 in cancer cells correlated with poor prognosis in GC patients." (PMID 31147602, 2019). "The chemokine CXCL8 (IL-8) is another important biomarker in many types of cancer." (PMID 31781510, 2019). "Besides, mast cells induce EMT and stem cell features in human cancer via the synthesis of CXCL8 (IL-8), a member of the chemokine family." (PMID 31579438, 2019). "IL-8, also known as CXCL8, is an important regulator of metastatic and advanced cancers." (PMID 29881400, 2018). "Since we expect more neoplastic cells in an area of clinical visible actinic keratoses, the superinduction of CXCL8 in neoplastic cancer cells could explain the stronger inflammatory reaction in these areas." (PMID 30266096, 2018).
cancer (continued). "Interestingly, in the function of migration of cancer cells, we found two significantly downregulated cytokine genes CXCL8 and IL11, and the network diagram showed that reduced CXCL8 and IL11 expression inhibited cell migration." (PMID 30578411, 2018). "Notably, in this study, it was found that CXCL8 overexpression is related to an improved overall cancer survival in GC patients." (PMID 30568862, 2018). "At present, CXCL8 is probably the most studied chemokine in human cancer." (PMID 29977225, 2018). "Taken together, these data strongly support the idea that CXCL8 might serve both as a potential therapeutic target and a clinical biomarker of some types of cancer." (PMID 29977225, 2018). "Functionally, DACH1 significantly suppressed CXCL8-induced migration of A549 and SKLU cells, which indicated that the cancer-promoting effects of CXCL8 could be attenuated by the expression of DACH1 in ADC." (PMID 29636079, 2018). "Recently, CXCL8 has been shown to act as an oncogene in several types of human cancers." (PMID 28883082, 2017). "We previously found that TAMs increased PTC cancer progression through CXCL8." (PMID 26875556, 2016). "The CM from cixutumumab-treated cancer cells failed to increase CXCL8 transcripts in Wi38 cells with an shRNA-mediated loss of IGF-2R expression and also in cells that had been incubated with neutralizing antibody blocking IGF-2R." (PMID 26465273, 2015). "Thus, the significance of CXCL8 in modulating the response of cancer cells to chemotherapy is still not fully understood." (PMID 24224100, 2013). "In particular, NFκB contributes to the initiation and progression of a wide variety of human cancers, through the regulation of genes that are involved in angiogenesis (e.g., CXCL8, VEGF), proliferation (e.g., cyclin D1), evasion of apoptosis (e.g., Bcl-2) and metastasis (e.g., MMP9)." (PMID 24276377, 2013). "Evaluated in cancer patients, CXCL8 expression might be used to assess the patient's prognosis and response to chemotherapy." (PMID 24224100, 2013). "Various signals and/or pathways induce CXCL8 expression in cancers." (PMID 24224100, 2013). "The ability of CXCL8 to mediate angiogenesis in many cancer types is well established." (PMID 24276377, 2013). "Furthermore, there is evidence to support a role of CXCL8 signaling in promoting the migration and invasion of cancer cells." (PMID 24276377, 2013). "Strategies to target these transcription factors and signaling pathways may therefore attenuate CXCL8 signaling in cancer cells indirectly, thereby sensitizing cancer cells to conventional therapeutic interventions." (PMID 24276377, 2013). "G31P can be used as an antagonistic agent to treat the carcinoma by reducing the level of CXCL8." (PMID 23586055, 2013). "Therefore, CXCL-8 potentially promotes the transcription of various extracellular matrix degrading enzymes in specific cancer cells, which facilitates their escape from primary sites." (PMID 23342280, 2012). "Moreover, the CXCL8 mRNA gradient ranged from cancer cells to TAM-enriched areas." (PMID 39905539, 2025). "In addition, HPV could regulate inflammatory chemokines (such as CXCL1-3, CXCL8), while OS contributes to viral DNA integration by promoting genome instability and cancer development." (PMID 40430101, 2025). "In addition to DAMPs, ICD inducers may promote the secretion of inflammatory cytokines such as IL6 and CXCL8 (IL8) from cancer cells." (PMID 39759512, 2024). "Finally, we reanalyzed data from the TCGA database to investigate whether CXCL8 expression was related to cancer progression." (PMID 39519144, 2024). "Therefore, the spatial distribution of CXCL8 expression in the TME could be important in furthering our understanding of the biology of CXCL8 in driving cancer progression." (PMID 35879507, 2022). "Thus, neutralizing antibodies to CXCL8 or antagonists towards CXCR1/2 to disrupt CXCL8–CXCR1/2 interaction may improve the efficacy of current cancer treatment." (PMID 36612163, 2022).
cancer (continued). "Furthermore, CD14CTX express certain molecules associated with immunosuppression such as CXCL8, TGFB1, and IL6, which could be targeted by anti-cancer therapy independently." (PMID 36130508, 2022). "Interestingly, the genes coding for chemokines such as CXCL1, CXCL2, CXCL3, and CXCL8 (IL-8) were strongly upregulated in CD4+ T cells co-cultured with cancer cells only, further suggesting the direct influence of cancer cells on chemokine expression in CD4+ T cells." (PMID 34439305, 2021). "CXCL8 (IL-8) may also be a potential therapeutic target in cancer." (PMID 34025668, 2021). "In keeping with that CXCL8 and ROS impact cancer progression and T cell survival, respectively, and that T cell expansion capability is a predictor of successful clinical expansion, selection of T cell subsets ahead of CAR T cell engineering could be a strategy to move the field forward." (PMID 33763058, 2021). "Finally, BRAF mutated cells also have angiogenic capacity, since they can induce other cancer cells and microenvironmental cells to secrete CXCL8 and CCL2, two pro-tumorigenic chemokines, leading to cancer cell proliferation and macrophage-mediated angiogenesis." (PMID 33193402, 2020). "Moreover, human neutrophils can in vitro produce CXCL8 upon co-culture with cancer cell lines." (PMID 32422991, 2020). "CXCL8/IL8 expression has been detected across several cancer indications including both solid and haematological malignancies and thus, one might speculate, whether CXCR2 transduction might not be as efficient in these malignancies as the CCR2 and CCR4 proposed above." (PMID 30126117, 2018). "In addition to the lack of a homologous genetic model, efforts to determine the function of CXCL8 in cancer progression are complicated by redundancy of the chemokines that share CXCR1 and CXCR2, and by the expression of cytokines other than CXCL8 in response to an upstream stimulus." (PMID 24224100, 2013). "Moreover, in response to stress, stromal cells produce CXCL8, which may influence the invasiveness and/or metastatic potential of cancer cells." (PMID 24224100, 2013). "According to one study, CXCL8 stimulates NET production by interacting with CXCR2, which in turn increases the migration and proliferation of cancer cells." (PMID 41503514, 2026). "In complete responders, skin lesion RNA sequencing after treatment, compared with baseline, identified increased inflammation (CXCL5, CXCL8, IL1A, COL1A1) and downregulated cancer markers (PRAME, S100B, MLANA, STK32A)." (PMID 42316430, 2026). "Chemokine CXCL1, also known as Gro-α and MGSA, a ligand of CXCR2, is the best-known CXC chemokine in cancer processes, after CXCL8/IL-8 and CXCL12/SDF-1." (PMID 41898553, 2026). "The single-cell sequencing bioinformatics analysis in this study found that CXCL8 (IL-8) expression was associated with c-FOS, which was consistent with previous studies that indicated that IL-8 could induce NETs, elevating the cascade effect exerted by NETs on cancer." (PMID 40148973, 2025). "HuMax-IL8 (BMS-986253), an inhibitor of CXCL8, has been demonstrated to be well-tolerated in patients with advanced cancers and is currently being evaluated for its safety and efficacy in combination with nivolumab (NCT03400332)." (PMID 39925807, 2025). "Increasing evidence has revealed that many factors secreted and produced by TAMs enhance cancer progression, such as EGF, PDGF, CXCL8, MMP9, and FGF2 in the TME." (PMID 40076874, 2025). "P. palaestina L. dramatically decreased levels of the chemokine C-X-C motif ligand 8 (CXCL8), which is involved in the growth of cancer cells." (PMID 40699792, 2025).